IL13RA2 (interleukin 13 receptor subunit alpha 2)
Diseases named in the same sentence as IL13RA2 in open-access papers (continued):
Sharing a sentence is not in itself a finding about the gene and the disease.
tumor (continued). "IL-13Rα2 does bind to IL-13 more readily than IL-13Rα1 and it is therefore hypothesized that GBM tumors potentially use IL-13Rα2 expression to bind up available IL-13 and prevent immune responses to the tumor cells by stimulating TGF-β production." (PMID 39329751, 2024). "The fast initial anti‐tumour responses in vivo may be mostly because of the interaction of CAR‐T cells with the IL‐13Rα2 positive tumours‐targeted component of the response." (PMID 38685487, 2024). "scFv‐IL‐13Rα2‐CAR‐T cells specifically killed IL‐13Rα2+ve but not IL‐13Rα2‐ve tumour cells in vitro and selectively caused significant release of IFN‐γ only from IL‐13Rα2+ve co‐cultures." (PMID 38685487, 2024). "Therefore, IL-13Rα2 is considered a tumor marker specifically expressed in various tumors owing to these characteristics." (PMID 39506843, 2024). "However, the recurrent tumor showed low expression of IL13Rα2, and therefore low target protein for CAR-T cells, and this is a major challenge for the use of this therapy in clinical practice." (PMID 39531784, 2024). "Thus, it is highly desirable to uniformly upregulate IL‐13Rα2 expression in tumours for optimal targeting by CAR‐T cells." (PMID 38685487, 2024). "Given that tumor cells can be selectively sensitized to Pep-1-Phor21 via the epigenetic up-regulation of IL-13Rα2, a combined adjuvant approach involving Pep-1-Phor21 and epigenetic inhibitors may be an effective strategy." (PMID 37345109, 2023). "Only 30% of patients with GBM harbor the EGFRvIII mutation, but fortunately, EphA2 and IL13Ra2 are not expressed in normal brain tissue, making it sufficient to target a CNS-specific and not necessarily a tumor-specific antigen." (PMID 37754534, 2023). "After IL-13 addition, PTP1B associates with IL13Rα2 Tyr369 to promote Src activation, which in turn activates PI3K through FAM120A, a scaffold protein promoting cell adhesion, migration, invasion, proliferation and survival in tumor cells." (PMID 37963919, 2023). "Additionally, histopathological analysis of tumor tissue from one patient before and after CAR-T cell administration indicated decreased IL13Ra2 expression within the tumor, further enhancing evidence of anti-tumor activity of anti-IL13Ra2 CAR-T cells." (PMID 36564524, 2023). "Preliminary results indicated decreased expression of IL-13Rα2 after tumor recurrence." (PMID 37443804, 2023). "Furthermore, Pep-1-Phor21 induced the rapid necrosis of tumor cells expressing cell-surface IL-13Rα2." (PMID 37345109, 2023). "The expression of IL13Rα2 in the tumor cells could be detected by the immunohistochemical analyses using anti‐IL13Rα2 antibody." (PMID 36806727, 2023). "Although the functional significance of IL-13Rα2 expression on tumor cells remains largely undefined, under certain circumstances, IL-13Rα2 signaling can mediate a variety of cellular and tissue responses that may impact tumorigenesis." (PMID 37345109, 2023). "Given that HDAC or DNMT inhibition selectively enhanced IL-13Rα2 expression in tumor cells, we further determined whether this effect translated into increased sensitivity to Pep-1-Phor21." (PMID 37345109, 2023). "CAR-T cells, unlike other adoptive T cell products facilitate MHC-independent tumor cell killing by allowing T cells to bind target cell surface antigens, for instance IL-13Rα2 in the present study, through a single-chain variable fragment (scFv) recognition domain." (PMID 37286997, 2023). "Therefore, unlike IL-13-PE38, Pep-1-conjugated drugs have the potential to specifically target IL-13Rα2-overexpressing tumours." (PMID 36830725, 2023). "Moreover, these cells can simultaneously target EGFRvIII and IL-13Rα2, two well-characterized tumor antigens highly expressed on the surface of GBM cells." (PMID 38067356, 2023).
tumor (continued). "More selective approaches to tumor therapy include targeting receptors that are upregulated in an oncogenic setting with one putative candidate being the cell-surface protein, interleukin-13 receptor α2 (IL-13Rα2)." (PMID 37345109, 2023). "While C2 (VWA1+) and C3 (IL13RA2+) were nearly derived from tumor tissues." (PMID 36483553, 2022). "One ongoing phase 1 clinical trial investigates the safety, efficacy, and feasibility of IL13Ra2 as a potential CAR T‐cell target in patients with recurrent or refractory malignant GBM due to its specificity for GBM tumor cells and limited expression on normal brain cells (NCT02208362)." (PMID 35844304, 2022). "IL13Rα2 promotes the activation of several pathways, such as MAPK, Akt/PKB, and Wnt/β-catenin, that induce cell invasion; therefore, the increased expression of IL13Rα2 was associated with an unfavorable prognosis in several neoplasms." (PMID 36143291, 2022). "In addition, expression of IL-13Rα2 and IL-13Rα2-mediated signaling has been shown to promote tumor proliferation, cell survival, tumor progression, invasion, and metastasis." (PMID 35464460, 2022). "IL13Ra2 is highly overexpressed on tumor cells in a high frequency of GBM patients." (PMID 36303101, 2022). "It has been shown in other disease contexts that expression of IL13Rα2 contributes to a more aggressive tumor phenotype, which could potentially explain this preferential attraction of T cells." (PMID 35939683, 2022). "Targeted IL13Rα2-expressing tumor cells and reduced overall IL13Rα2 expression." (PMID 35692797, 2022). "Overexpression of IL-13Rα2 was found in 66% of tumor samples from 80 CC patients." (PMID 33450900, 2021). "Similarly in a murine GBM model intraventricular administration of IL13Rα2-specific CAR T cells was found to convey greater control of the contralaterally grafted tumor." (PMID 34113233, 2021). "Finally, a combined expression of EphA2, EphA3, EphB2 and IL-13RA2 is observed in almost every GB patient, presenting in tumor-infiltrating cells, tumor-initiating cells or GSCs and neovasculature." (PMID 34209513, 2021). "The authors of the study targeted HER2 and IL13Rα2, two commonly found tumor antigens." (PMID 34572775, 2021). "The results of immunohistochemical staining showed IL-13Rα2 expression in ATC tissue, which distributed in both the cytoplasm and cell membrane; in contrast, IL-13Rα2 was undetectable either in cytoplasm or outer membrane of normal thyroid tissue adjacent to tumor region." (PMID 33457193, 2021). "In turn, this may cause global transcriptomic changes, given our finding that overexpression of KMT5B restored H4K20me2 patterns and decreased the expression of several oncogenes, such as IL13RA2, a tumor-restricted receptor." (PMID 34447744, 2021). "In contrast, medium (n = 5) IL-13Rα2 expression was associated with a 20% survival rate of ACC subjects with tumor metastasis while ACC subjects with medium (n = 20) IL-13Rα2 expression and no metastasis showed a 70% survival rate (p = .1206)." (PMID 33591997, 2021). "In a murine GBM model, simultaneously targeting HER2 and IL-13Rα2 showed better tumor control." (PMID 33673696, 2021). "We evaluated the relationship between IL-13Rα2 expression and tumor progression in animal models." (PMID 34201539, 2021). "These peptide targeting CAR T cells resulted in anti-tumor effects in orthotopic xenograft models including tumors that did not express typical GBM associated tumor antigens such as IL13Rα2." (PMID 34421912, 2021). "In one subject, IL-13Rα2-targeted CAR T treatment altered the tumor microenvironment (TME) by activating the host immune system to target the tumor through enhanced IFN-γ signaling after CAR treatment, which subsequently resulted in subsequential complete response in the subject." (PMID 35011583, 2021).
tumor (continued). "Thus, in vivo mouse models of human PDA indicate that IL-13Ra2 is one of the key-signature genes participating in tumor invasion and metastasis." (PMID 34201539, 2021). "The anti-IL-13Rα2 antibody reduced tumor metastasis and prolonged the prognosis in this model." (PMID 34201539, 2021). "Inhibition of apoptosis of tumor cells that selectively express IL-13Rα2 suggests that IL-13Rα2 may act as an oncogene." (PMID 33591997, 2021). "Of note, intracranial administration of CAR T cells targeting interleukin-13 receptor alpha 2 (IL-13Rα2) resulted in robust antitumor immunity and complete tumor regression in one patient with recurrent multifocal glioblastoma, which sustained for 7.5 mo following CAR T cell infusions." (PMID 32235752, 2020). "Based on our previous studies, IL-13Rα2 has a critical role in tumor invasion and metastasis." (PMID 32443847, 2020). "Furthermore, IL-13RA2 is expressed in the mesenchymal-type tumor cells within the GBM microenvironment." (PMID 32340173, 2020). "Interestingly, generation of a tri-cistronic transgene encoding three CAR molecules against HER2, EphA2 and IL13Rα2, dubbed universal CAR-T (UCAR), was shown to overcome interpatient heterogeneity and target 100% of tumor cells." (PMID 33154756, 2020). "Taking this approach one step further, the same research group generated trivalent CAR-T cells targeting HER2, IL-13Rα2, and EphA2, which could overcome the interpatient variability and capture nearly 100% of tumor cells." (PMID 33767690, 2020). "Accordingly, the IL-13Rα2 expression by tumor cells correlates with metastases in multiple cancers." (PMID 33233582, 2020). "Multivariate analysis revealed that only four parameters including IL-13Rα2 expression, UICC-stage, tumor differentiation, and invasion of lymph duct (Ly), and three parameters that included IL-13Rα2 expression, UICC-stage, and CA19-9 were independent prognostic factors." (PMID 32443847, 2020). "We observed that only tumor cells showed appreciable IL-13Rα2 immunostaining." (PMID 32443847, 2020). "Targeting IL-13RA2 alone showed therapeutic benefit by rendering the tumor as less invasive." (PMID 32340173, 2020). "Based on our previous studies suggesting that inhibition of IL13Rα2 delays tumor growth and suppresses formation of lung metastases, we wanted to investigate whether depletion of INHBA has a similar effect on metastatic MIV cells." (PMID 30805303, 2019). "A safety and efficacy trial of CAR T cell therapy in GBM with IL-13Ra2 as the tumor marker was performed on a group of three patients who had a post-resection intracranial infusion, followed by a trial of post-resection direct intratumoral infusion followed intraventricular infusion [61, 62•]." (PMID 30790064, 2019). "However, IL13Rα2 expression was observed only in a subset of tumour cells (≤10% tumour cells) in >50% tissue samples showing positive IL13Rα2 staining." (PMID 30718742, 2019). "While high level of IL13Rα2 expression inhibited cell proliferation in vitro, it also promoted the expression of amphiregulin, a proangiogenic factor, which in turn resulted in enhanced angiogenesis and increased tumour formation in vivo." (PMID 30718742, 2019). "Intriguingly, in mice treated with IL13-Rα2.IL-15-CAR T cells, tumors recurred at late time points and the majority of relapsed tumors no longer expressed IL-13Rα2, implicating antigen loss as a tumor escape mechanism in this model." (PMID 30828333, 2019). "In addition to EGFRvIII, EphA2, IL-13Ra2, and HER2, several other tumor-associated antigens have previously been explored as targets for GBM therapies in preclinical models." (PMID 30740109, 2018). "Nude mice were used for tumour growth and survival analysis after treatment with IL13Rα2 peptides." (PMID 30318506, 2018). "The outcome could potentially be improved if enrolled patients could be limited only to ones with over expressed IL-13Rα2 in tumor tissue." (PMID 29168083, 2018).
tumor (continued). "As a gene that is highly expressed in tumor infiltrating macrophages (TIM) and tumor-associated macrophages (TAM), but shows minimal expression in normal brain tissue, IL13Rα2 has been previously studied as a cancer vaccine, and more recently as a direct target for CAR therapy." (PMID 30031396, 2018). "Next, an siRNA knockdown approach was used to assess whether the CHI3L1/IL‐13Rα2 axis might be responsible for PCa tumor cell invasiveness driven by monocyte‐CM." (PMID 30094958, 2018). "This property indicates that IL-13Rα2 could serve as a promising targeted moiety for anti-tumor drug delivery." (PMID 30723412, 2018). "Another potential tumor target of CAR T cells is represented by IL13Rα2." (PMID 30279357, 2018). "In our previous study, we demonstrated that Pep-1 conjugated paclitaxel (PTX) loaded nanoparticles, could be internalized into tumor cells via IL-13Rα2 mediated endocytosis." (PMID 30723412, 2018). "Pep-1 peptide (CGEMGWVRC) that was screened by the phage display library, could bind to IL-13Rα2 with high affinity and specificity and could be exploited to target ligand to tumor cells." (PMID 30723412, 2018). "In addition, the similar median survival results were obtained between the patients group with IL-13Rα2 low tumor and the patients group with IL-13Rα2 high tumor treated with temozolomide." (PMID 29168083, 2018). "Similarly, analysis of the mouse sciatic nerves after tumor induction revealed significant expression of IL13Rα2 by IHC when compared to a normal sciatic nerve." (PMID 29304038, 2018). "Our in vitro and in vivo experiments with peripheral nerve sheath tumor cells and animal models clearly suggest that targeting the IL13Rα2 with IL13 conjugated liposomes will increase the accumulation of the drug in the tumor and subsequently decrease the tumor burden." (PMID 29304038, 2018). "The same group subsequently reported a case study where they observed regression of an IL13Rα2-positive multifocal GBM tumor in a patient treated with intraventricular administrations of second generation IL13Rα2-CAR T-cells that also express CD137 intracellular domain as part of the CAR construct." (PMID 30740109, 2018). "And secondly, despite the incredible radiological response, the patient relapsed with tumours that had significantly decreased IL13Rα2 expression suggesting that antigenic heterogeneity may be a significant hurdle to the success of this approach." (PMID 29854316, 2018). "The physical magnetic targeting and IL-13Rα2 mediated active targeting characteristics could synergistically increase the targeted efficiency for a tumor." (PMID 30723412, 2018). "IL-13 receptor α2 (IL-13Rα2) is a promising non-mutant GBM-associated antigen due to its broad tumor expression and extremely low expression levels in normal brain." (PMID 30740109, 2018). "Therefore, the focus of this study is to radiolabel Pep-1L, a novel peptide isolated from a hepta-peptide library that specifically binds to IL13RA2 and determine its in vitro and in vivo tumor binding properties." (PMID 28881623, 2017). "Therefore, to validate Pep-1L as an in vivo IL13RA2 targeting platform, we utilized PET/CT molecular imaging to visualize real-time Cu-64 labeled Pep-1L binding to a standard IL13RA2-expressing tumor." (PMID 28881623, 2017). "The expression of IL-13Rα2 was mainly localized in tumor cells." (PMID 27351230, 2016). "We therefore investigated whether CD11b+ cells and M2Mφs recruited into tumours following irradiation express IL-13Rα2." (PMID 27271009, 2016). "Interestingly, the percentage of IL-13Rα2+ cells in CD11b+ cells in tumours grown at pre-IR sites was significantly higher than that of non-IR sites." (PMID 27271009, 2016). "Patients with higher expression of IL-13Rα2 in tumor tissues were prone to lower OS." (PMID 27351230, 2016). "We next investigated the effects of IL13Rα2 on tumor growth and metastasis in vivo." (PMID 26418721, 2015).
tumor (continued). "Thus, our data confirmed that Ad5FFscFv47-CMV-GFP is capable of specific transduction of IL13Rα2-expressing tumor cells not only in vitro but also in vivo." (PMID 26656559, 2015). "In addition to these theories, our data suggested that IL13RA2 expression was correlated with tumor growth and sensitivity to sunitinib." (PMID 26114873, 2015). "Additionally, tumor growth in vivo was significantly suppressed by shRNA-mediated knockdown of IL13RA2." (PMID 26114873, 2015). "IL13Rα2 positive expression in tumor tissues was observed in 79 of 181 (43.6%) NSCLC patients." (PMID 26418721, 2015). "IL-13 binding to IL13Rα2 increased tumor migration and invasion." (PMID 26418721, 2015). "All patients had positive IL-13Rα2 expression in ≥30% of the tumor cells as determined by IHC." (PMID 25767039, 2015). "Next we studied the effects exerted by IL13Rα2 on tumor cell migration and invasion." (PMID 26418721, 2015). "Importantly, depletion of IL13Rα2 resulted in a modest but consistent delay in primary tumor growth and dramatically suppressed lung metastasis formation in vivo." (PMID 26208975, 2015). "Therefore, it would be valuable to determine if IL-13Rα2 acts as a core factor to control the dual axes of YKL-40/IL-13Rα2 and IL-13/IL-13Rα2 in tumor malignancy." (PMID 26439689, 2015). "IL13RA2 was identified as a candidate molecule associated with sunitinib resistance in our model KURC1, and IL13RA2 expression was significantly higher in human primary ccRCC tumor of patients with sunitinib-resistant metastatic sites." (PMID 26114873, 2015). "Additionally, immunohistochemical analyses were performed for two antigens (IL13Rα2, Fra-1) overexpressed at mRNA level in the majority of the original tumours." (PMID 25788865, 2014). "Expression of IL-13Rα2 was reduced in the tumors while, concurrently, the spleens of the treated mice show reduced numbers of MDSCs, a population of myeloid cells that aid in tumor immune evasion." (PMID 23421960, 2013). "Although the functional significance of IL13Rα2 expression by malignant gliomas is not well understood, it has been shown to promote tumor migration and invasion, and protect tumor cells from apoptosis thereby contributing to tumor growth." (PMID 24204956, 2013). "Our results suggest that IL-13Rα2 cDNA boosted with ECDα2 protein vaccination may enhance anti-tumor-immunity by inhibiting the suppressive effects of Tregs." (PMID 21067607, 2010). "IL-13Rα2 is overexpressed on certain types of human tumor tissues." (PMID 21067607, 2010). "This antibody may be directly cytotoxic to tumor cells or mediate growth inhibitory signal to target cells after ligating with IL-13Rα2 antigen." (PMID 21067607, 2010). "Furthermore, ECDα2 booster vaccination increased IFN-γ production and CTL activity against tumor expressing IL-13Rα2." (PMID 21067607, 2010). "We now provide evidence that IL-13Rα2 is highly expressed in a variety of murine tumor cell lines." (PMID 21067607, 2010). "However, each tumor cell-restimulated splenocytes collected from mice receiving the IL-13Rα2 DNA vaccine boosted with ECDα2 produced substantial levels of IFN-γ in the culture supernatant and was capable of mediating specific lysis of each target cells." (PMID 21067607, 2010). "Thus, IL-13Rα2 can serve as a potent tumor antigen that can recruit immune responses against IL-13Rα2 expressing solid tumors." (PMID 21067607, 2010). "However, dupilumab may promote tumor progression by blocking IL-13Rα1 and then increasing IL-13 binding to IL13Rα2, thus promoting tumor progression in some tumors, especially CTCLs." (PMID 39758935, 2025). "In contrast to other GBM-associated surface antigens, such as HER2, EGFRvIII and IL-13Rα2 are unique because they are frequently expressed in GBM cells but are absent or present at very low levels in somatic tissues, reducing the likelihood of on-target, off-tumor toxicity." (PMID 40092990, 2025).